ABCA1 (ATP binding cassette subfamily A member 1)
Diseases named in the same sentence as ABCA1 in open-access papers (continued):
Sharing a sentence is not in itself a finding about the gene and the disease.
atherosclerosis (continued). "Research findings suggested that ABCA1 and ABCG1 are key transporters that facilitate cholesterol egress from macrophages, reducing atherosclerosis development." (PMID 34445501, 2021). "To date, the function of ABCA1 and ABCG1 transporters is best known in the pathogenesis of the comorbid course of COPD and atherosclerosis." (PMID 34201488, 2021). "ABCA1 plays a particularly significant role in these processes, participating in the pathogenesis of COPD and atherosclerosis, which most studies are devoted to." (PMID 34201488, 2021). "This happens via induction of the ATP-binding cassette transporters ABCA1 and ABCG1, which initiate macrophage reverse cholesterol transport and prevent atherosclerosis." (PMID 34868038, 2021). "Studies from our groups and others have revealed that increased ABCA1 and ABCG1 expression contributes to alleviation of lipid accumulation and atherosclerotic lesions in atherosclerosis-prone mice." (PMID 33692340, 2021). "SDT with 5-aminolevulinic acid as a sonosensitizer (ALA-SDT) activates the PPAR-γ-LXRa/ABCA1 and ABCG1 pathway, increasing cholesterol efflux, induces an anti-inflammatory response, and ultimately reduces the signs of atherosclerosis." (PMID 34940525, 2021). "We also noted that BMDM–HG-exo reduced the expression of Abca1 that is central to promoting cholesterol efflux from macrophages and HSPC preventing their expansion and contribution to atherosclerosis." (PMID 34381972, 2021). "Consistently, ablation of macrophage ABCA1 and ABCG1 in mice resulted in a substantial increase in atherosclerosis progression." (PMID 34445501, 2021). "We expect to promote the study of the role of ANXA1 in atherosclerosis and sincerely hope that more scientists will study the relationship of ABCA1 with ANXA1 and atherosclerosis development." (PMID 32894039, 2020). "Besides, Qu can also affect the expression of LXRα and ABCA1 through the p38-dependent pathway, proprotein convertase subtilisin/kexin type 9 (PCSK9) pathway, and cholesterol 7 alpha-hydroxylase (CYP7A1) pathway to promote cholesterol efflux and reduce the risk of atherosclerosis." (PMID 32565865, 2020). "In a study investigating the potential of bexarotene in atherosclerosis, the mRNA levels of both NPC1L1 and ABCA1 were found to be reduced in the duodenum and jejunum of bexarotene-treated mice, supporting our findings." (PMID 32308567, 2020). "On the one hand, they regulate the formation of foam cells by inhibiting ATP-binding cassette transporter A1 (ABCA1); on the other hand, they affect endothelial dysfunction by suppressing KLF2, and jointly promote the formation of atherosclerosis." (PMID 32070413, 2020). "Activation of the PPARγ/LXRα signaling pathway has been shown to increase ABCA1 and ABCG1 expression and thereby mitigate atherosclerosis." (PMID 33959213, 2020). "We think the changes of AER and ABCA1-independent CEC at 1- and 5-years are likely to be biologically relevant to the progression of atherosclerosis." (PMID 32260470, 2020). "Although ABCA1 mediates ANXA1 release, the effect of this function on atherosclerosis has been unclear." (PMID 32894039, 2020). "Further studies need to focus on the role of ABCA1-mediated ANXA1 efflux and ANXA1-mediated ABCA1 expression in the development of atherosclerosis." (PMID 32894039, 2020). "Our study demonstrates that HMGB1 promotes CUMS-induced atherosclerosis via activating TLR4 signaling, which drownregulates the expression of PPARγ-LXRα-ABCA1." (PMID 30881312, 2019). "Therefore, the mechanisms by which NGM282 protects against atherosclerosis may be multifactorial and are not limited to the selective activation of hepatic LXR, the promotion of HDL biogenesis via ABCA1, and the associated impact on reverse cholesterol transport and systemic inflammatory status." (PMID 30679232, 2019).
atherosclerosis (continued). "This study investigated the effects of Cav on exosome expression and function, ATP-binding cassette transporter A1 (ABCA1) expression, and cholesterol efflux that are relevant to the process of atherosclerosis." (PMID 31635197, 2019). "Our results revealed that HMGB1 is a critical signal for TLR4-mediated the down-regulation of PPARγ/LXRα-ABCA1, which accelerates CUMS-induced atherosclerosis." (PMID 30881312, 2019). "miR-33a/b is co-expressed with SREBP1/2 and miR-33a dysregulation is thought to contribute to atherosclerosis by promoting lipid build-up and cholesterol retention in macrophages through the ATP binding cassette (ABC) transporter ABCA1." (PMID 31847094, 2019). "ATP-binding cassette A1 (ABCA1) plays a key role in generating high-density lipoprotein (HDL) and preventing atherosclerosis." (PMID 30872611, 2019). "Hemodynamic changes that occur during the development of atherosclerosis, including low sheer stress and turbulent flow, alter the expression of both LXR isoforms and their target genes Abca1 and Abcg1." (PMID 30087224, 2018). "Therefore, we propose that NE promotes atherogenesis by degrading ABCA1 protein, resulting in increased monocytosis, macrophage migration, and foam cell formation, which, in turn, leads to a higher level of local and systemic inflammation, and eventually increases atherosclerosis." (PMID 29437605, 2018). "Activation of the LXRα-ABCA1/ABCG5/8 pathway exerted anti-inflammatory and lipid-regulatory effects during atherosclerosis [reviewed in Fessler (2018)]." (PMID 29593532, 2018). "Due to its ability to enhance ABCA1-dependent reverse cholesterol transport, LXR is an attractive target for the treatment of atherosclerosis." (PMID 29593532, 2018). "Our results showed that overexpression of salusin-α increased the expression of positive regulators of atherosclerosis (ABCA1 and ABCG1) and inhibited negative regulators of atherosclerosis (ACAT1 and CD36)." (PMID 30105261, 2018). "The ATP-binding cassette transporter A1 (ABCA1) is a key transporter for ChE and its increased expression is regarded to attenuate atherosclerosis." (PMID 28659806, 2017). "Notably, the expression of ABCA1 in peripheral blood monocytes inversely correlates with the extent of atherosclerotic disease, suggesting that epigenetic silencing of ABCA1 gene expression in monocytes and macrophages may contribute to atherosclerosis." (PMID 27295295, 2016). "Some studies have shown that ABCA1 and ABCG8 in the liver can prevent atherosclerosis by enhancing HDL biogenesis and hepatic cholesterol excretion." (PMID 27869741, 2016). "ABCA1 and ABCG1 transporters thus play a synergistic role in preventing atherosclerosis and cardiovascular disease, making them a useful marker for healthy aging." (PMID 27545843, 2016). "The overexpression of hepatic Abca1 in transgenic mice results in a marked increase in HDL release, decreased LDL and significantly reduced atherosclerosis when compared with control mice." (PMID 27488580, 2016). "Chronic activation of TRPV1 by capsaicin increased ATP-binding cassette transporter A1 (ABCA1) and reduced LDL-related protein 1 (LRP1) expression in aorta, thus attenuating atherosclerosis." (PMID 27455231, 2016). "The induction of ATP-binding cassette transporter family members, such as ABCA1 and ABCG1, by LXR activation can enhance reverse cholesterol transport and reduce atherosclerosis." (PMID 27250582, 2016). "Nevertheless, it is now well-approved that ABCA1, ABCG1, and SR-BI represent three major key players in atherosclerosis." (PMID 27252658, 2016). "For example, activation of the Liver X receptor (LXR) signaling pathway regulating the ABCA1/ABCG1 expression have been shown to promote macrophage RCT and decrease atherosclerosis in mouse models." (PMID 27252658, 2016).
atherosclerosis (continued). "Given our findings that macrophages show decreased ABCA1-mediated efflux upon reduction of PRMT2, studies that examine the effects of PRMT2 directly on atherosclerosis and diabetes are now warranted but beyond the scope of this study." (PMID 26288135, 2015). "Some studies have assessed the respective roles of liver ABCA1 and ABCG8 in preventing atherosclerosis by promoting HDL biogenesis and hepatic cholesterol excretion." (PMID 26318157, 2015). "Although cholesterol lowering is a way to decrease lipid retention, increasing lipid efflux from macrophages, mostly through ABCA1 and ABCG1, has been regarded as another significant strategy to limit atherosclerosis." (PMID 24999295, 2014). "Overexpression of ABCA1 and ABCG1 limits atherosclerotic plaque formation, while genetic deletion of these genes promotes foam cell formation and accelerates atherosclerosis in animal models." (PMID 24999295, 2014). "Furthermore, we identify Abca12 as a mediator of Abca1-regulated cellular cholesterol efflux, a finding that may have significant implications for other diseases of lipid metabolism and homeostasis, including atherosclerosis." (PMID 18802465, 2008). "This article aims to explain the relationship between oxidative stress and lipid homeostasis, showing how ROS damage to the ABCA1 and ABCG1 transporters disrupt RCT, thereby contributing to the development and progression of atherosclerosis and other metabolic disorders." (PMID 41300518, 2025). "Furthermore, it has been shown that PPARγ augments ABCA1/G1 and SR-B1 expression to inhibit MDFC formation and exert an anti-atherosclerosis effect." (PMID 40867523, 2025). "Recently, Zulong found visceral adipose tissue‐derived exosomes in high‐fat diet‐fed obese mice promoted macrophage foam cell formation and M1 macrophage transition, decreased macrophage‐regulated cholesterol efflux via downregulation of ABCA1 and ABCG1, and further exacerbated atherosclerosis." (PMID 40045164, 2025). "Our results showed that by upregulating the PPARγ-ABCA1/ABCG1/SR-B1 pathway, ART could enhance cholesterol efflux and ameliorate inflammation, thereby alleviating atherosclerosis." (PMID 40867523, 2025). "PPAR-γ/LXR, the key pathway known to regulate the expression of ABCA1/ABCG1, has been identified could enhance cholesterol efflux, thereby attenuating atherosclerosis." (PMID 40537740, 2025). "For instance, mice lacking ABCA1 and SR-B1 exhibit hypocholesterolemia and foam cell accumulation but do not develop atherosclerosis." (PMID 40384967, 2025). "This could account for the reduced activity of ABCA1 and ABCG1, clarifying the pathophysiology of atherosclerosis and potential therapeutic targets." (PMID 41300518, 2025). "Numerous studies have shown that ABCA1 plays an essential role in reverse cholesterol transport (RCT) in macrophages by stimulating the efflux of cholesterol, thereby reducing foam cell formation and the progression of atherosclerosis." (PMID 40526435, 2025). "The deletion of ABCA1 and ABCG1 in macrophages accelerates the development of atherosclerosis in LDL receptor-knockout mice, underscoring the pivotal role of cholesterol efflux mediated by ABCA1 and ABCG1 in preventing atherosclerosis." (PMID 40537740, 2025). "Maria Franca Mulas and colleagues found that PBMCs from patients with atherosclerosis or familial hypercholesterolemia showed enhanced cholesterol esterification, increased lipid accumulation, and reduced Cav-1, n-CEH, and ABCA1 expression compared with controls." (PMID 41425976, 2025). "However, the transporter ATP-binding cassette subfamily A, member 1 (ABCA1), can remove cholesterol from these intimal, cells reducing atherosclerosis." (PMID 39765632, 2024). "Accordingly, increasing expression of cholesterol export proteins such as ATP-binding cassette subfamily A, member 1 (ABCA1), may enhance cholesterol efflux and impede atherosclerosis development." (PMID 39765632, 2024).
atherosclerosis (continued). "Furthermore, 5-aminolevulinic acid-mediated sonodynamic therapy improves cholesterol efflux via activating PPARγ–LXRα–ABCA1/ABCG1 signaling pathways, enhancing efferocytosis and cholesterol efflux, and eventually ameliorating atherosclerosis." (PMID 38699583, 2024). "Indeed, the overexpression of either ABCA1 or ABCG1 heightens HDL levels and confers protection against atherosclerosis." (PMID 38474781, 2024). "In addition to activating PPARα signaling, many TCM prescriptions stimulate PPARγ–liver X receptor (LXR) α–ABCA1/ABCG1 signaling pathways, thereby ameliorating lipid profiles and atherosclerosis through upregulation of reverse cholesterol transport (RCT)." (PMID 38699583, 2024). "ATP-binding cholesterol transporters ABCG1 and ABCA1 export cholesterol from macrophages in the vessel wall to HDL and ApoA-1, reducing lipid deposition and preventing foam cell formation, thereby attenuating atherosclerosis (Ouimet, Barrett & Fisher, 2019)." (PMID 39421410, 2024). "In addition, quercetin protects against atherosclerosis via regulation of PCSK9 as well as LXRα and ABCA1." (PMID 37997262, 2024). "As the major contributors to cholesterol efflux, ABCA1 and ABCG1 are responsible for approximately 70% of cholesterol release from lipid‐rich macrophages, thereby playing a critical role in protecting against macrophage lipid accumulation and atherosclerosis." (PMID 39698913, 2024). "In mice lacking ApoE, HSP72 accelerates the development of atherosclerosis by inhibiting the production of ABCA1 and ABCG1 in peritoneal macrophages and the aorta through the JNK/Elk-1 pathway." (PMID 37077734, 2023). "Since the formation of macrophage foam cells is influenced by the balance between modified LDL uptake and cholesterol efflux, we investigated the effects of SFN on cholesterol efflux and the expression of ABCA1 and ABCG1 in this atherosclerosis-prone genetic mouse model." (PMID 37432260, 2023). "The overexpression of ABCA1 in mice increased plasma HDL levels and prevented atherosclerosis." (PMID 36674699, 2023). "Previous studies found that the manipulated deletion of the ABCA1 gene exacerbates the development of atherosclerosis, while ABCA1 overexpression promotes RCT, suggesting that ABCA1 may play an essential role as an atherosclerosis suppressor in vivo." (PMID 36830597, 2023). "The purpose of this study is to investigate whether SFN treatment could influence macrophage foam cell formation and atherosclerosis and explore the potential mechanistic contribution of CD36, ABCA1/G1 expression and the involvement of PPARγ and Nrf2." (PMID 37432260, 2023). "This inhibition, which was attributed to downregulation of Abca1 gene and ABCA1 protein expression, suggested that PCSK9 can also have extrahepatic effects that may influence relevant steps in the pathogenesis of atherosclerosis." (PMID 36067830, 2022). "Free cholesterol is either effluxed from cells to HDL (reverse cholesterol transport) via the lipid transporters ABCA1 and ABCG1, key players in atherosclerosis, or trafficked to the ER, where it is reconverted into cholesteryl esters and stored in lipid droplets." (PMID 34876704, 2022). "In addition, the ABCA1 and ABCG1 transporters are an important link between COPD and atherosclerosis." (PMID 35897703, 2022). "However, the effect of cholesterol efflux pathways mediated by ATP-binding cassette A1 and G1 (ABCA1/ABCG1) on T cell-dependent age-related inflammation and atherosclerosis remains poorly understood." (PMID 35778407, 2022). "Taken together, FTY720 induces ABCA1 expression through SphK2-mediated acetylation of H3K9 and suppresses lipid accumulation in macrophages, which provides novel insights into the mechanisms of action of FTY720 on atherosclerosis." (PMID 36498944, 2022).
atherosclerosis (continued). "In atherosclerosis, oxysterols derived from phagocytosis of apoptotic or necrotic cells activate the LXR pathway in naive macrophages, upregulating genes involved in cholesterol efflux, such as ATP binding cassette A1 (ABCA1)." (PMID 35219337, 2022). "Loss of ABCA1 causes the rare Tangier disease, which leads to impaired cholesterol export, especially in macrophages, lack of HDL-cholesterol and development of atherosclerosis." (PMID 35328615, 2022). "These SNPs (APOA‐I, ABCA1, and SR‐BI) disrupt the pathway of HDL biogenesis and may lead to dyslipidemia and atherosclerosis in mice." (PMID 36171780, 2022). "Therefore, further studies are needed for the effect of ABCA1 on CVD risks and the development of atherosclerosis." (PMID 35498045, 2022). "Surprisingly though, studies involving the whole-body and tissue-specific deletion and overexpression of ABCA1 and ABCG1 have been conflicting when evaluating whether these two transporters protect against atherosclerosis." (PMID 35625607, 2022). "Given that miR-92a promotes atherosclerosis by targeting ABCA1, it is suggested that TUG1 may compete with ABCA1 for binding to miR-92a to reduce ABCA1 expression." (PMID 36011386, 2022). "Leukocyte ABCA1 has been shown to play an important role in protecting against atherosclerosis, whereas more widespread and larger atherosclerosis lesions develop in the absence of ABCA1 leukocyte." (PMID 36363640, 2022). "Taking into account that the downregulation of SIRT1 decreases the transcription of ABCA1, the activation of SIRT1 may be considered as a potential therapy for atherosclerosis and CVD." (PMID 34940525, 2021). "Fortunately, other strategies to upregulate ABCA1 protein in endothelial cells, such as using LXR and RXR agonists, may prove to be effective treatments for atherosclerosis." (PMID 34564456, 2021). "Thus, promotion of ABCA1- and ABCG1-mediated cholesterol efflux is a key mechanism by which CTRP12 suppresses macrophage lipid accumulation and mitigates atherosclerosis." (PMID 33692340, 2021). "For ABCA1, lncRNA CDKN2B-AS1 also significantly decreases the ABCG1 level in human foam cells, inhibiting the expression of CDKN2B, which can lead to the suppression of RCT and progression of atherosclerosis." (PMID 34940525, 2021). "In fact, recent findings found that reduced ABCA1 expression in the macrophages, by proprotein convertase subtilisin/kexin type 9 (PCSK9), could accelerates atherosclerosis, thereby inhibiting RCT." (PMID 33766036, 2021). "In an in vitro study, CXCL8 enhances the expression of miR-183, which then inhibits ABCA1 expression and cholesterol efflux, suggesting that the CXCL8-miR-183-ABCA1 axis may play an transitional role in the development of foam cells in atherosclerosis." (PMID 33503867, 2021). "Furthermore, ox-LDL activated LXRs promote the outflow of cholesterol via upregulating transporters, such as ABCA1 and ABCG1, in macrophages, thereby alleviating atherosclerosis." (PMID 34026849, 2021). "Thus, a decrease in the lipid transport function of ABCA1 in macrophages, both in the bronchi and in the vascular wall, is an important link in the development of COPD and atherosclerosis." (PMID 34201488, 2021). "ABCA1, ABCG1, and HDL are potential targets for the treatment of atherosclerosis." (PMID 34350368, 2020). "For example, a knockout of ABCA1 aggravated the formation of FCs but did not promote atherosclerosis plaque development." (PMID 33240650, 2020).